BRCA1 (BRCA1 DNA repair associated)
Diseases named in the same sentence as BRCA1 in open-access papers (continued):
Sharing a sentence is not in itself a finding about the gene and the disease.
breast cancer (continued). "In the French population, in breast carcinoma patients who are younger than 46 years old, the BRCA1/2 mutation prevalence was 9.1% (BRCA1 = 6.5% and BRCA2 = 2.6%)." (PMID 30713775, 2019). "Among the 8 patients with breast carcinomas in second-degree relatives, only 1 patient (12.5%) had a BRCA1 mutation." (PMID 30713775, 2019). "In high genetic risk breast carcinoma patients, the BRCA1 and BRCA2 germline mutations were identified by applying next-generation sequencing." (PMID 30713775, 2019). "In the Turkish population, all high-risk breast carcinoma patients should absolutely be evaluated in terms of BRCA1/2 mutations." (PMID 30713775, 2019). "In the British population, in patients with breast carcinomas who are younger than 36 years old, the BRCA1/2 mutation prevalence was 5.9% (BRCA1 = 3.5% and BRCA2 = 2.4%)." (PMID 30713775, 2019). "Overall, in the Turkish population, the BRCA1/2 mutation prevalence ranges from 19% to 37% in patients with high-risk breast carcinomas." (PMID 30713775, 2019). "In conclusion, in the Turkish population, the total BRCA1/2 mutation positivity prevalence was 19% in the patients with high-risk breast carcinomas." (PMID 30713775, 2019). "In the patients with breast carcinoma histories in their second-degree relatives, the BRCA1 mutation prevalence was 12.5%." (PMID 30713775, 2019). "In those with first-degree relatives with breast carcinoma histories, the BRCA1/2 mutation prevalence was also 19%." (PMID 30713775, 2019). "The BRCA1/2 mutation prevalence in women with breast carcinomas is higher in patients under 40 years of age." (PMID 30713775, 2019). "Hereditary breast cancers arise from mutations of the tumor suppressor gene BRCA1, and share histological features with triple-negative breast cancer (TNBC) and basal-like breast cancers (BLBCs)." (PMID 30213113, 2018). "Eligible patients for this study were healthy women with ≥ 17% lifetime risk of breast cancer or with a mutation in BRCA1 or BRCA2." (PMID 29318406, 2018). "Given the detection of a pathogenic BRCA1 mutation, she started cancer screening at a young age in a breast cancer unit." (PMID 30518416, 2018). "Pathogenic BRCA1 founder mutations (c.4035delA, c.5266dupC) contribute to 3.77% of all consecutive primary breast cancers and 9.9% of all consecutive primary ovarian cancers." (PMID 29928469, 2018). "We have recently estimated the risk of breast cancer among BRCA1 mutation carriers among women of Polish decent who were carriers of one of three founder mutations." (PMID 30572612, 2018). "The present study demonstrates a clear protective effect of early first pregnancy on breast cancer risk in women with pathogenic BRCA1 or BRCA2 mutations." (PMID 29116468, 2018). "In contrast, a study from Norway reported 10 deaths in 68 BRCA1 mutation carriers at a median follow-up of 4.2 years for an estimated five-year breast cancer specific survival of only 75% and 10-year survival of 69%." (PMID 30513626, 2018). "Additional experiments will be necessary to evaluate this combination strategy in other tumors such as BRCA1-mutated cancer and somatic breast cancer showing a BRCAness phenotype." (PMID 30038706, 2018). "Although somatic mutations are rare in sporadic breast cancers, BRCA1 dysfunction has also been reported in a large number of these cases." (PMID 30323899, 2018). "Latinas affected by breast cancer have the second highest prevalence of BRCA1/2 mutations after Ashkenazi Jews." (PMID 30227649, 2018). "Pathogenic variants in highly penetrant hereditary breast cancer genes, such as BRCA1 and BRCA2 are known to account for 5–10% of breast cancer in the general population." (PMID 30287823, 2018).
breast cancer (continued). "This is particularly relevant in BRCA1-deficient breast cancers, which lack effective DNA repair mechanisms through homologous recombination and are therefore susceptible to genetic modification induced by ROS." (PMID 29868481, 2018). "Penetrance of the mutations involving the BRCA1 gene and breast cancer is more expressive than that for the BRCA2 gene and ovarian cancer." (PMID 30517521, 2018). "In contrast, the application of the upper age limit for triple-negative breast cancer patients of 40 years (Swedish Breast cancer group criteria for screening for mutations in BRCA1 and BRCA2) would miss several BRCA-positive cases in our cohort." (PMID 29928469, 2018). "Luminal progenitors are expanded in BRCA1 mutation carriers and linked to basal-like breast cancers, whereas stem- and progenitor-enriched basal cells are associated with claudin-low breast cancers." (PMID 29921600, 2018). "Using subcellular fractionation analysis on purified mitochondria, we have found that in breast cancer cells the metabolic switch is speeded up in response to the presence of a peculiar mutation on BRCA1 gene." (PMID 29584711, 2018). "Estimated cumulative breast cancer risk by age of 70 conferred by pathogenic variants in BRCA1 and BRCA2 is approximately 60 and 50%, respectively." (PMID 30410870, 2018). "About 5–10% of all breast cancer (BC) cases are due to inherited predisposition, and about 20–40% of these cases are caused by germline mutations in BRCA1 and BRCA2 genes." (PMID 29884136, 2018). "The tumor suppressors BRCA1/2 play an important role in DNA repair, and mutations in BRCA1/2 are found in familial as well as sporadic breast cancers." (PMID 29531804, 2018). "In our study, genetically unstable BRCA1 deficient breast cancer cells exhibited enhanced proliferation, migration and invasion compared to BRCA1 wild type breast cancer cells, when co-cultured with cmCAFs." (PMID 30224826, 2018). "BRCA1 has been considered a risk-related gene for breast cancer, and the studies included in our meta-analysis reveal that the BRCA1 rs799917 polymorphism plays an important role in the risk of non-breast cancer, especially in Asian populations." (PMID 29492227, 2018). "Due to a contralateral breast cancer 20 years after the initial diagnosis, the patient underwent germline BRCA1 mutation testing, revealing the same pathogenic mutation in BRCA1." (PMID 29453630, 2018). "Testing for germline BRCA1/2 mutations has an established predictive role in breast cancer risk assessment." (PMID 29867226, 2018). "In this study, we co-cultured primary CAFs (isolated from human breast cancer patient tissues) with BRCA1 deficient and proficient cancer cells in vitro and demonstrated that CAFs can be converted to MAFs in the presence of BRCA1 defective cancer cells." (PMID 30224826, 2018). "The BRCA1 mutant SUM149PT breast cancer cells had a lower mutation rate with 608 ± 146 acquired base substitutions, which again did not alter due to niraparib treatment (p = 0.56)." (PMID 30425352, 2018). "In this study, we demonstrated that termite kings express higher levels of the breast cancer susceptibility gene BRCA1 than other castes." (PMID 30312170, 2018). "Patients having two or more first-degree relatives with ovarian cancer usually have an early onset of the disease, especially with the breast cancer gene 1 and 2 (BRCA1 and BRCA2) germline mutations or Lynch syndrome." (PMID 30050740, 2018). "Estrogen activated EMT in a subset of Brca1-deficient mammary tumor cells that maintained epithelial features, and enhanced the number of cancer stem cells, promoting tumor progression and metastasis." (PMID 29996906, 2018). "Among carriers of mutations in BRCA1/2, there is a higher probability of occurrence of breast cancer of the TNBC phenotype." (PMID 30040829, 2018).
breast cancer (continued). "The breast cancer 1, early onset (BRCA1) gene is frequently mutated in familial breast cancers and women harbouring these germline mutations have an increased risk of developing breast cancer." (PMID 30323899, 2018). "This is illustrated by a study in which monozygotic (MZ) twins who carried identical BRCA1 gene mutations, resulted in discordant phenotypes: One had breast cancer twice in 27 years while her MZ twin remained healthy." (PMID 30249004, 2018). "In the metastatic setting, using platinum agents to treat BRCA1/2-associated breast cancer appears to be a reasonable option, even after the first line of treatment." (PMID 30544963, 2018). "BRCA1/2 mutations are known to increase the lifetime risk of breast cancer by 50-87% and ovarian cancer by 10-40%, based on data derived primarily from Caucasians." (PMID 29861850, 2018). "Studies have shown that hereditary breast cancer (e.g., BRCA1 and 2 mutations) are frequent in breast cancers in young women, but the prevalence of high penetrance gene mutations was lower in Asian populations." (PMID 29324832, 2018). "Breast cancer risk for BRCA1 and BRCA2 pathogenic mutation carriers is modified by risk factors that cluster in families, including genetic modifiers of risk." (PMID 29422015, 2018). "Previous studies have reported that mammary tumors that spontaneously develop in BRCA1-deficient mice can be orthotopically transplanted into female mice without loss of their original phenotype, gene expression profile, or sensitivity to anticancer agents." (PMID 30327455, 2018). "Founder mutations in the two breast cancer genes, BRCA1 and BRCA2, have been described in many populations, among these are Ashkenazi-Jewish, Polish, Norwegian and Icelandic." (PMID 29339979, 2018). "The levels of HIF-1α in the mitochondrial fraction of BRCA1 mutated breast cancer cells is significantly increased compared to sporadic models." (PMID 29584711, 2018). "The mutation prevalence of BRCA1/2 mutation carriers in Japanese individuals is higher than that in the USA except for the groups with male breast cancer." (PMID 29176636, 2018). "As PM can reduce risk of breast cancer by > 90%, it is often performed among BRCA1/2 mutation (BRCA1/2MUT) carriers." (PMID 30203341, 2018). "Women with breast cancer associated with a germline mutation of BRCA-1 usually present with a tumor of triple-negative phenotype." (PMID 29875927, 2018). "The cohorts investigated reflect a general population but included also women with a high familial risk of breast cancer and BRCA1-mutation carriers (4 benign and 4 malignant samples)." (PMID 29849944, 2018). "We examined intrinsic subtypes of breast cancer in BRCA1/2 mutation carriers based on the information about their ER, PgR, and HER2 status." (PMID 29176636, 2018). "The primary aim of this study was to determine the effect of a germline BRCA1 or BRCA2 mutation on breast cancer outcomes in patients with young-onset breast cancer." (PMID 29337092, 2018). "To date, there are no available data from randomized trials that specifically target BRCA1 gene mutation carriers with breast cancer." (PMID 29719582, 2018). "In women who carry the BRCA1 mutation the chances of getting breast cancer are around 65% and with BRCA2 they are around 40% (AIOM)." (PMID 30061853, 2018). "For determining the fibroblast-induced tumorigenicity, we co-cultured CAFs and NFs (n = 20) with the BRCA1 proficient and deficient breast cancer cells." (PMID 30224826, 2018). "BRCA1 inherited mutation carriers face a lifetime risk of 72% to develop breast cancer and a percentage of 44% risk for ovarian cancer." (PMID 30340058, 2018). "Most of the articles focused on the risk of developing ovarian and breast cancer, by examining the presence of BRCA1 and BRCA2 mutations." (PMID 30619456, 2018). "The mean age at breast cancer diagnosis was 40.1 years for BRCA1 and 44.4 years for BRCA2 mutation carriers." (PMID 29937543, 2018).
breast cancer (continued). "Cumulative cancer risks at age 70 years were breast cancer risk of 57% for BRCA1 and 49% for BRCA2 mutation carriers; and ovarian cancer risk of 40% for BRCA1 and 18% for BRCA2 mutation carriers." (PMID 30263092, 2018). "Approximately 70% of breast cancers arising in BRCA1 mutation carriers and up to 23% of breast cancers in BRCA2 carriers are triple-negative." (PMID 29514593, 2018). "In individuals harboring mutations in BRCA1, the probability of developing breast cancer over a lifetime is about 57–65% and that of ovarian cancer is about 39–40%." (PMID 29459887, 2018). "For example, mutational signature analysis in breast cancers revealed that promoter methylation of RAD51C had a similar effect on HR deficiency as biallelic inactivation of BRCA1/2." (PMID 30497521, 2018). "Breast cancers generated in a CK14-Cre Brac1f/f/p53f/f mouse were also found to be similar to human BRCA1-deficient tumors, with a minority being adenomyoepitheliomas." (PMID 29874626, 2018). "This investigation will support to develop strategies to inhibit estrogen synthesis and to target AKT for treatment of BRCA1-deficient basal-like breast cancers." (PMID 29996906, 2018). "We undertook a prospective, single-arm study of comprehensive BRCA1/2 mutation screening in a consecutive series of unselected patients with newly diagnosed breast cancer (BRCAsearch, ClinicalTrials.gov Identifier: NCT02557776)." (PMID 29164420, 2018). "The association between exposure to ovarian stimulation for IVF and the incidence of breast cancer in BRCA1/2 mutation carriers was examined in only one previous study." (PMID 29937543, 2018). "Deleterious BRCA1 mutations have been identified in two patients of European origin with primary breast cancer and melanoma." (PMID 30286154, 2018). "The effect of in vitro fertilisation (IVF) on breast cancer risk for BRCA1/2 mutation carriers is rarely examined." (PMID 29937543, 2018). "Mutations in BRCA1 protein were first identified in familial breast cancer, and BRCA1 has since been established as a strong breast and ovarian cancer susceptibility gene, responsible for approximately half of all inherited breast cancer cases." (PMID 29757984, 2018). "Breast cancer developed in 622 of 1535 BRCA1/2 mutation carriers (40.5%) who had completed their first pregnancy between 21 and 47 years of age had developed breast cancer after their FFTP but before 50 years of age." (PMID 29116468, 2018). "Germ-line mutations in breast cancer susceptibility gene, BRCA1, result in familial predisposition to breast and ovarian cancers." (PMID 29426838, 2018). "The proband developed the first breast cancer at the age of 40, while the sister, with only the BRCA1 mutation, had an age of diagnosis of 56 years." (PMID 29346284, 2018). "The few studies on genetic susceptibility for breast cancer in the Sri Lankan population have focused mainly on the BRCA1 and BRCA2 genes." (PMID 29433565, 2018). "A meta-analysis of available studies in Asian women revealed pooled estimates of breast cancer risk by age 70 of 44.8% (95% CI 33-57.2%) and 40.7% (95% CI 31.3-50.9%) for BRCA1 and BRCA2 mutation carriers respectively." (PMID 29861850, 2018). "They focus BRCA1/2 associated breast cancer, and make the mistake of considering the two very different forms of breast cancer associated with BRCA1 and BRCA2, respectively, to be biologically similar disorders." (PMID 28939999, 2018). "A recent paper described the difference between efficacy and effectiveness with regard to the identification of BRCA1/2 mutation carriers amongst women diagnosed with breast cancer." (PMID 29344385, 2018).
breast cancer (continued). "In total, 938 of 2514 women (37.3%) were diagnosed with breast cancer, 630/1550 BRCA1 (40.7%) and 308/964 BRCA2 mutation carriers (32.0%)." (PMID 29937543, 2018). "Mutations in BRCA1/2 genes account for 20 to 25% of all hereditary breast cancers and about 5–10% of all breast cancers." (PMID 29433453, 2018). "In this regard, the integration of several genome-wide datasets of ENCODE, TCGA, and GEO can allow for identification of the BRCA1-associated genetic elements for development as putative prognostic markers for breast cancer." (PMID 29757984, 2018). "We undertook the Prospective Outcomes in Sporadic versus Hereditary breast cancer (POSH) study, the primary aim of which was to determine the effect of inherited BRCA1 or BRCA2 mutations on outcomes in patients with young-onset breast cancer." (PMID 29337092, 2018). "BRCA1/2 mutation testing thus has important and expanding roles in treatment planning for subsets of patients with breast cancer." (PMID 29867226, 2018). "The data thus far suggests that tamoxifen has a role in estrogen-receptor blockade and the prevention of a contralateral breast cancer, even among BRCA1 mutation carriers who have a tendency to develop this hormone-receptor negative disease." (PMID 30572612, 2018). "The oncogenic miR-155 has been found to be epigenetically repressed in breast cancer by BRCA1, DNA repair associated (BRCA1), which recruits HDAC2 on the miR-155 promoter." (PMID 29401683, 2018). "This is the first study to investigate the association of selected genetic polymorphisms in breast cancer related genes (apart from BRCA1 and BRCA2) and the susceptibility to sporadic breast cancer in the Sri Lankan population." (PMID 29433565, 2018). "In line with previous studies relative to the rare double heterozygosity in both BRCA1/2 genes, we found the earlier onset of breast cancer in our patient with both BRCA1/2 mutations with respect to other relatives carrying the single BRCA1 mutation." (PMID 29346284, 2018). "We will also conduct a meta-analysis to integrate available estimates of breast cancer risk in Asian women carrying a BRCA1 or BRCA2 germline mutation into a consensus estimate of penetrance." (PMID 29861850, 2018). "Breast cancer is the second leading cause of death among American women; it is estimated that in the US the genetic testing designed to reveal the presence of BRCA1 gene is performed on about 250,000 women annually." (PMID 29445722, 2018). "Twelve female patients with BRCA1 gene mutations who had stage I to III breast cancers were eligible for evaluation." (PMID 29719582, 2018). "For BRCA1 mutation carriers, the risk of breast cancer increased substantially between the ages of 30–50, while for women with a BRCA2 mutation, the risks were highest between ages 40–60." (PMID 30572612, 2018). "Among the 51 patients who underwent PM, 6 had specimens in which occult breast cancer was found, including 1 with a BRCA1 mutation and 5 with BRCA2 mutations." (PMID 30203341, 2018). "This trial included 14 breast cancer (all with deleterious BRCA1/2 mutations) treated with talazoparib at 1 mg/kg." (PMID 30544963, 2018). "For example, if the parents receive findings regarding breast cancer because of mutations in BRCA1 or BRCA2 genes, it can conflict with the child’s right to an open future if knowledge is disclosed that the child would have wanted to live without as an adult." (PMID 29506557, 2018). "In the present study, we demonstrate for the first time that CAFs isolated from primary breast cancer tissues when co-cultured with BRCA1 mutated HCC1937 cells transform CAFs to MAF in vitro." (PMID 30224826, 2018). "Our previous results showed that less than 10% of the clinically high risk breast cancer patients harbor BRCA1 and BRCA2 mutations, and importantly, nearly half of the mutations were recurrent mutations." (PMID 29487695, 2018).